CD4 (CD4 molecule)
Diseases named in the same sentence as CD4 in open-access papers (continued):
Sharing a sentence is not in itself a finding about the gene and the disease.
mental disorder (13 papers, 2013 to 2025). A disease that has its basis in the disruption of mental process. "In SA, most LYL associated with any mental disorder occurred at CD4 counts ≥350 cells/μl, whereas in NA, most losses occurred at CD4 counts <350 cells/μl." (PMID 40826829, 2025). "Jun N-terminal kinase pathway-associated phosphatase (JKAP) regulates CD4+ T-cell differentiation and immunity, which are linked to mental disorders." (PMID 39383378, 2024). "In contrast, among individuals with severe mental disorders and substance use disorders, unnatural deaths and natural deaths at CD4 cell counts below 200 play a more significant role." (PMID 40826829, 2025). "Among PLHIV and mental disorders, male gender, low baseline CD4 cell count, being divorced or widowed, and poor adherence were associated with low viral suppression." (PMID 37726822, 2023). "Adherence to ART and low CD4 at ART initiation are associated with viral suppression among PLHIV and mental disorders." (PMID 37214962, 2023). "The CXC chemokine receptor CXCR3 controls CXCL9, CXCL10, and CXCL11 induced leucocyte trafficking to inflammatory sites, and reduced CXCR3 expression on CD4+ T cells and CXCR3+ CD4+ T cell numbers have been found in mental disorders." (PMID 36226111, 2022). "Peripheral CD4+ T cells have been reported as the major contributors to the occurrence of mental disorders." (PMID 35836182, 2022). "Moreover, peripheral CD4+ T cells have been reported as the major contributors to the occurrence of mental disorders." (PMID 35836182, 2022). "Equally important, one might speculate the existence of CD4+ T-cell-specific factors that control emotional behaviors and their exploitation for the treatment of wide variety of mental disorders." (PMID 23838891, 2013). "Among PLHIV and mental disorders, older age increased likelihood of VLS, male gender, low baseline CD4 cell count, being divorced or widowed, and poor adherence were associated with low viral suppression." (PMID 37214962, 2023). "For individuals with common mental disorders, interventions should focus on improved management of physical comorbidities to reduce mortality at higher CD4 cell counts, which are unlikely to be HIV‐related." (PMID 40826829, 2025). "Therefore, we excluded the current CD4+ cell counts and HIV RNA levels, leaving nine stratification factors that showed significant variations in the proportion of any mental disorders for further network analyses." (PMID 34744844, 2021). "However, our findings do not support this hypothesis, as individuals diagnosed with mental disorders had a higher baseline CD4 cell count than those who did not receive mental health diagnoses." (PMID 40826829, 2025).
peanut allergy (13 papers, 2013 to 2024). "These clusters (cluster 131 from optimized run or cluster 143 from default run) was annotated as a subpopulation of naive CD4+ T cells that play an essential role in peanut allergy as its frequency was decreased during allergic sensitization." (PMID 39445014, 2024). "In a mouse model of peanut allergy, CD4+ CD25+ T cell-depleted mice showed impaired oral tolerance upon the exposure to peanuts and induced an IgE-mediated food hypersensitivity response after an oral challenge." (PMID 34835940, 2021). "In a small, DBPC trial investigating the effectiveness of OIT for peanut allergy among 28 patients (1–16 years), the number of CD4+CD25+FOXP3+ Tregs was significantly increased after 1 year of treatment compared to baseline in peanut OIT patients." (PMID 33224138, 2020). "Since then, an allergen-specific T cell subset of memory TH2 cells that are CD4+CD45RO+CD27−CD45RB+CD161+CD49d+ have been described of importance in peanut allergy." (PMID 33224138, 2020). "Confirmation in a larger cohort of patients is now needed to determine if levels of CYP11A1 mRNA in activated CD4+ T cells can serve as a predictor of peanut allergy." (PMID 32497050, 2020). "The relevance of the Ara h component-specific CD4 TH2 cell responses in “predicting” peanut allergy was also evaluated by using receiver operating characteristic (ROC) analysis." (PMID 29988522, 2018). "CD4+ T cells play a major role in the pathophysiology of peanut allergy as well as tolerance induction during oral desensitization regimens." (PMID 30304054, 2018). "The pathophysiology of peanut allergy involves the participation of peanut-specific CD4+ T-cells." (PMID 39204201, 2024). "In addition, we have previously shown that the frequency of peanut-reactive CD154+CD4+ T cells in patients with peanut allergy is correlated with the patients’ clinical sensitivity, illustrating the specificity of this assay." (PMID 34813505, 2022). "In addition, OIT to peanut allergy has shown to induce the differentiation of novel CD4+ T cell subsets." (PMID 32060620, 2020). "Understanding the peanut-specific CD4 T cell responses in peanut-allergic (PA) subjects should provide new insights into the development of innovative immunotherapies for the treatment of peanut allergy." (PMID 29988522, 2018). "We aimed to design peptides based on the most reliably recognized CD4+ T cell epitopes of major peanut allergens for a T cell-targeted immunotherapy for peanut allergy as a safe (non-IgE reactive) and effective alternative to whole allergens." (PMID 23711131, 2013). "Similarly, we have recently shown in a mouse model of epicutaneous immunotherapy for peanut allergy that Foxp3 methylation was reduced upon successful EPIT, while methylation of the Th2 key transcription factor Gata3 was specifically increased in splenic CD4+ IL4+ T cells." (PMID 32060620, 2020).
psychological distress (13 papers, 2014 to 2026). "Moderate stressful events, low social support, number of negative life events of six or more, not disclosing HIV status, and severe and moderate levels of CD4 cell count were independently associated with generalized psychological distress." (PMID 24852246, 2014). "Unlike two cross-sectional studies conducted among PLHA receiving ART, this study found that CD4 counts ≥200 cells/mm3 and between 200 and 499 cells/mm3 were both associated with psychological distress." (PMID 24852246, 2014). "From clinical factors, HIV-seropositive patients with a CD4 cell count of less than 200 cells/mm3 (OR=4.33, 95% CI 1.49–13.42) and a CD4 cell count between 200 and 499 (OR=3.32, 95% CI 1.73–6.35) were associated with psychological distress." (PMID 24852246, 2014). "Being female, illiteracy, alcohol use, having lower CD4 count, and perceived stigma increased the odds of psychological distress." (PMID 31428472, 2019). "Being female, illiteracy, alcohol use, and having lower CD4 count and perceived stigma increased the odds of psychological distress." (PMID 31428472, 2019). "Another factor which was responsible for the development of psychological distress is CD4 cell count less than 500 cells/μl." (PMID 31428472, 2019). "Multivariate logistic regression analysis revealed that being a female, illiteracy, current alcohol usage, CD4 count less than 500 cells/μl, and perceived stigma were statistically significant with psychological distress (p < 0.05)." (PMID 31428472, 2019). "In the STIAL study, a brief measure of psychological distress (the MHI-5), was associated with a small decreased risk in linkage to care (defined as obtaining a CD4 count, conditional upon registering at an ART centre)." (PMID 24981595, 2014). "Psychological distress predicted lower antiretroviral adherence (est.=-0.070, p = 0.033), which was associated with higher log HIV RNA viral load (est.=-0.477, p < 0.001) and lower CD4 count (est.=84.754, p < 0.001)." (PMID 41831113, 2026). "RCTs showed that yoga could decrease psychological distress, and increase quality of life and CD4 counts immediately after the intervention." (PMID 31185970, 2019). "Moderately stressful events, low social support, negative life events, not disclosing HIV status, and low and moderate levels of CD4 cell count are independent risk factors associated with psychological distress." (PMID 24852246, 2014). "To gain mechanistic insights, we assessed whether CD4+ T-cell immune activation could be related to signalling from the central nervous system, by examining the relationship between CD4+ T-cell activation, chronic gut symptoms, psychological distress and stress hormones." (PMID 30842618, 2019).
psychosis (13 papers, 2016 to 2025). "Alterations in the proportions of circulating DCs, CD45RA- Tregs, CD4+ central memory T cells, and CD4+ CD161+ naïve T cells were consistently implicated as immune markers of psychosis by both PLS analyses." (PMID 27244229, 2016). "This would mirror results in human studies that also showed decreased proportions of natural killer cells, CD4+ T-cells and CD8+ T-cells in psychosis-associated patients." (PMID 36061196, 2022). "Previous studies have reported that the number of CD4+CD27+CD28+ cells in elderly patients with psychosis is lower than that in young patients." (PMID 34955935, 2021). "Shown are forest plots from meta-analyses of differences in blood cell proportions derived from DNA methylation data between psychosis patients and controls for (A) monocytes, (B) granulocytes, (C) natural killer cells, (D) CD4+ T-cells, and (E) CD8+ T-cells." (PMID 33646943, 2021). "Eighty-eight per cent of HIV-infected patients with psychosis had CD4 count results recorded in the psychiatric chart." (PMID 30263214, 2018). "Motivated by the importance of central nervous system dopamine signalling for psychosis, we measured dopamine receptor gene expression in separated CD4+ cells." (PMID 27244229, 2016).
T-cell immunodeficiency (13 papers, 2009 to 2025). A broad classification of disorders that affect the cell-mediated aspect of the immune response. "T cell immunodeficiencies included DiGeorge syndrome thymic aplasia, low CD4+ T cell count associated with HIV disease, Wiskott-Aldrich syndrome and more." (PMID 41001471, 2025). "It is well-known that CD4+ T cells play a central role in coordinating innate and adaptive immune responses, as demonstrated by the susceptibility to pathogenic and OIs resulting from primary or acquired CD4+ T cell immunodeficiency." (PMID 31574798, 2019). "A greater number of type 1 and type 17 polarized CD4+ compared to CD8+ T cells was observed during immunocompetency and during T cell immunodeficiency as well." (PMID 36229573, 2022). "Although it will be important to establish why memory CD4+ T cell replenishment eventually fails in more pathogenic HIV and SIV infection, our results also indicate that there is still CD4+ T cell immunodeficiency even though numbers of memory CD4+ T cells are not reduced at the population level." (PMID 19943952, 2009).
thymic lymphoma (13 papers, 1996 to 2022). "As expected HSCT combined with a clinically relevant non-myeloablative host-conditioning regimen inhibited development of thymic lymphomas prolonging the lifespan of Atm-deficient mice through the restoration of the CD4 as well as the CD8 T-lymphocyte populations over time." (PMID 31849966, 2019). "The overexpression of GATA3 in T cells during development in thymic lymphoma directs DP cells towards CD4 lineage, enhances lymphoma development, and increases thymocytes size in CD2-Gata3 transgenic mice." (PMID 35681778, 2022). "This study demonstrates that RIPK3 acts as a negative regulator of thymic lymphoma initiation and progression by inhibiting the proliferation of abnormal CD4+CD8+ DP thymocytes." (PMID 36161785, 2022). "NA in the absence of TCR rearrangement therefore allows asynchronous thymic development to the CD4/8 DP stage and development of cortical thymic lymphoma." (PMID 26753883, 2016). "In the absence of Rag-mediated TCR rearrangements, NPM–ALK can induce ‘T cell maturation' to the CD4+CD8+ double-positive (DP) and CD4 single-positive (SP) stages of T-cell development, allowing the formation of thymic lymphomas." (PMID 26753883, 2016). "Conditional deletion of Fbxw7 in CD4+ cells, or deletion of Nr4a3 and the closely related Nr4a1, resulted in hyper-proliferation of T cells, thymic lymphoma's and lethal lymphoproliferation, a phenotype similar to Foxp3−/− mice." (PMID 23825948, 2013). "Mice with CD4- CD8+ tumours succumbed to thymic lymphoma at a significantly younger age than mice developing CD4+ CD8+ tumours." (PMID 8554976, 1996). "We now demonstrate that CD4-driven NPM–ALK can lead to both bypass of the RAG2−/−-mediated murine DN3 thymic maturation block and to the development of cortical thymic lymphoma." (PMID 26753883, 2016). "The developed monoclonal thymic lymphomas are CD3+, CD4+, and CD8+/low, suggesting a DP origin." (PMID 35681778, 2022). "However, in Brca1−/−;Trp53bp1−/− mice that were viable with no obvious symptoms at 5 months, early stage thymic lymphomas containing CD4 and CD8 double positive lymphocytes were frequently observed." (PMID 32139898, 2020).
viral myocarditis (13 papers, 2016 to 2025). Myocarditis that is caused by an infection with a viral agent. "CD4+ T cells undergo activation and differentiation into four distinct subsets, namely Th1, Th2, Th17, and Tregs, in the context of viral myocarditis." (PMID 40234407, 2025). "Multiple investigations have confirmed that the proportion and differentiation of CD4+ Th cells are closely related to the development of viral myocarditis." (PMID 36827455, 2023). "Abnormalities in CD4+ T cell (Th cell) differentiation play an important role in the pathogenesis of viral myocarditis (VMC)." (PMID 33380272, 2021). "CD4 T cells play crucial roles in mediating adaptive immunity, and dysregulated CD4 T cells and miRNAs affected the pathogenesis of viral myocarditis." (PMID 33809362, 2021). "In fact, this study confirmed the role of ip inhibitors for steering CD4+ T cell differentiation towards a suppressive phenotype with more regulatory T cells and higher expression of PD-1 in spleen tissue, also during viral myocarditis." (PMID 33523326, 2021). "The results of this study indicated the regulatory effect of the CAP on the differentiation of CD4+ T cells in viral myocarditis." (PMID 30176160, 2018). "Recently, many researchers found that CD4+ T cell subsets, including Th1, Th2, Th17, and Treg, play an important role in viral myocarditis, and the functions of each subgroup varied in myocarditis." (PMID 30176160, 2018). "CD4+ T cells and their subgroups mediate adaptive immunity, participating in the development and progression of viral myocarditis." (PMID 30176160, 2018). "Many studies have found that abnormalities in the proportion and differentiation of CD4+ T cells (Th cells) are closely related to the pathogenesis of viral myocarditis (VMC)." (PMID 30176160, 2018). "The monocytic myeloid-derived suppressor cells upregulated the percentages of Treg and CD4+ IL-10+ T cells to reduce the inflammatory response in viral myocarditis." (PMID 30176160, 2018). "Importantly, KEGG enrichment analysis revealed downregulated pathways in both CD4+ and CD8+ T cells that are associated with viral myocarditis, and various autoimmune conditions in C57BL/6 as compared to A/J mice." (PMID 41301818, 2025). "Similar to viral myocarditis, in AM of A/J mice, the ip stimulates the production of chemotactic and pro-inflammatory cytokines, the later governing CD4+ T cell differentiation into Th17 and Th1 cells in autoimmune heart disease and cumulating in cardiac tissue damage and dysfunction." (PMID 33523326, 2021). "In this research, we proposed that the CAP could regulate the differentiation of CD4+ T cells in viral myocarditis." (PMID 30176160, 2018). "Taken together, our data suggest that the early induced IL-10 and IL-10+ CD4+ Tregs in the cecal patch after CVB3 infection intimately regulate intestinal IL-10 and IL-10+ CD4+ Tregs situation, thus exerting an important pro-viral and pro-inflammatory effect in the development of viral myocarditis." (PMID 37896753, 2023).
acquired immunodeficiency (12 papers, 2012 to 2025). "Particularly, the specific role of CD4+ T cells in responses against the commensal fungus Candida albicans (C.albicans) is underscored by the fact that primary and acquired immunodeficiencies that lead to the impairment of CD4+ T cell immunity can cause pathogenic C.albicans infections." (PMID 32636404, 2020). "The HIV-1 virus causes acquired immunodeficiency by selectively infecting and killing CD4+ T cells." (PMID 24860567, 2014). "As an immunocompromised individual with acquired immunodeficiency, the patient experienced a decline in CD4+ T cells, contributing to disease progression." (PMID 40538739, 2025). "HIV infection leads to a fall in the numbers of CD4+ T cells with the subsequent acquired immunodeficiency." (PMID 22411458, 2012). "Thus, an acquired immunodeficiency in CD4 T-cell function develops, leading to increased proliferation of latent EBV cells, which increases the risk of neoplastic transformation or autoimmune disease in these tissues." (PMID 37718435, 2023). "In addition, three of the seven participants in the primary/acquired immunodeficiency group were people with HIV on antiretroviral therapy with CD4 lymphocyte counts >500 cells/mm3." (PMID 37910527, 2023). "Thus, acquired immunodeficiency by HIV infection, which selectively depletes CD4+ T cells, leads to increased risk of developing many different types of cancer, some related to known infections, and others unrelated." (PMID 24860567, 2014). "HIV-infected individuals suffer a decline in CD4 T cell numbers, leading to an acquired immunodeficiency that could halt the development of the inflammatory reaction responsible for SO." (PMID 22411458, 2012). "These are two conditions that classify patients as having acquired immunodeficiency status of HIV infection, and therefore are often found in patients with low CD4 count." (PMID 30867046, 2019). "Fludarabine monophosphate depletes CD4 cells, altering the CD4:CD8 ratio and producing a syndrome that is clinically and immunologically similar to acquired immunodeficiency." (PMID 24385727, 2012). "Furthermore, in our model of acquired immunodeficiency in CD4 T-cell function, CD8 T cells are “exhausted” and do not respond well to stimuli without the help of CD4 T cells." (PMID 37718435, 2023).